H19 (H19 imprinted maternally expressed transcript)
Diseases named in the same sentence as H19 in open-access papers (continued):
Sharing a sentence is not in itself a finding about the gene and the disease.
tumor (continued). "Our results revealed that down‐regulation of H19 significantly inhibited tumour growth and enhanced the effect of pemetrexed and cisplatin or Gefitinib in NSCLC in vivo." (PMID 32281297, 2020). "In many tumor studies, lncRNA H19 is considered to be an oncogenic gene and performed high expression in aggressive growth hormone-secreting pituitary adenomas (GHPAs)." (PMID 32192168, 2020). "H19 even supports MET (mesenchymal epithelial transition) to promote tumor proliferation and colonization either in primary or in the secondary site." (PMID 33193379, 2020). "An experimental metastasis model using a murine model of ATC unveils the functions of H19 lncRNA mediated tumour growth and metastasis." (PMID 33126409, 2020). "The lncRNA H19 expression level in tumor tissues was significantly higher than that in the adjacent normal tissues (P < 0.01) which was consistent with previous reports." (PMID 32509581, 2020). "Evidence indicates that plasma H19 levels can be used to distinguish patients with early GC from controls, with clinical results that are as satisfactory as traditional tumor biomarkers." (PMID 32754285, 2020). "By analyzing the public database, H19 was one of most overexpressed lncRNAs in primary tumor and metastatic tissues compared with adjacent normal tissues in CRC." (PMID 32698890, 2020). "H19 overexpression decreases colonoy formation, indicating a tumor cell survival suppressing and chemotherapy-sensitizing action of H19." (PMID 32429417, 2020). "Early reports suggested that H19 functioned as a tumor suppressor capable of inhibiting cell growth." (PMID 31616462, 2019). "During tumor cell proliferation, the transcription factor E2F induces H19 expression by binding its promoter, thereby accelerating the G1-S transition and the cell cycle." (PMID 31340867, 2019). "H19 includes five exons and four introns, and plays an important role in embryonic and tumor development." (PMID 31480503, 2019). "Using this approach, targeting H19 significantly inhibited metastatic tumor progression by approximately eightfold." (PMID 31299871, 2019). "H19 was reported to regulate tumor metastasis and EMT by miR-29b-3p as competing endogenous RNA in bladder cancer." (PMID 30728351, 2019). "Recently, some studies have reported that H19 is a tumor suppressor in PTC cells, but other study has reported that H19 is a tumor promotor in PTC cells." (PMID 31791180, 2019). "In PTC tissues, H19 was significantly higher than paired paracancerous tissue or normal tissues, and overexpression of H19 was correlated with higher tumor burden of PTCs." (PMID 31299871, 2019). "Numerous studies have shown that H19 can be used as a potential tumor marker for targeted therapy of malignant tumors, including PTCs." (PMID 31299871, 2019). "For example, DTA-H19, a double-stranded DNA plasmid, carries the gene for the diphtheria toxin A subunit, which causes cell death by immediately ending gene translation and the H19 promoter limits its expression to tumor cells." (PMID 31615976, 2019). "At the same time, it appears to be in line with our results in terms of H19 downmodulation observed under combined treatment and with the known key role played by hypoxia and estrogen in tumor aggressiveness." (PMID 31426484, 2019). "Higher expression of H19 was correlated with tumor recurrence and is considered as prognostic factors for disease free survival, regardless of other confounders." (PMID 31767907, 2019). "As H19 lncRNA is highly upregulated in several cancers, a plasmid containing diphtheria toxin under the control of H19 regulatory sequences has been designed to selectively target tumor cells which overexpressed H19 compared to normal cells." (PMID 31653018, 2019). "H19 can function as both a tumor suppressor or oncogene and also as a regulator of growth and development in multiple mammalian embryo tissues." (PMID 31737629, 2019).
tumor (continued). "Compared with the si‐NC group, a marked decrease in the volume and weight of tumour tissues was detected in the si‐lncRNA H19 group (P < .05)." (PMID 31317666, 2019). "The function of H19 is still controversial, exhibiting a promoting role in oncogenesis, but also acting as a tumor suppressor." (PMID 31426484, 2019). "H19 has been identified as one of the lncRNAs involved in tumorigenesis, however, its role in tumor proliferation has been controversial for a long time." (PMID 31787851, 2019). "The long non-coding RNA (lncRNA) H19 can function either as a tumor promoter or as a tumor suppressor, depending on the type of cancer, development stage, or molecular background." (PMID 31299871, 2019). "In contrast, H19 overexpression promotes cell proliferation and migration in BC cell, and increases tumor growth and metastasis in vivo." (PMID 31480503, 2019). "Of note, H19 level was demonstrated to be significantly promoted by HIF under hypoxic tumor environments." (PMID 31170091, 2019). "Clinical relevance of H19 has been related with poor recurrent free survival (RFS) tumor differentiation and advanced TNM stage, and is an independent predictor for OS and DFS." (PMID 31632922, 2019). "Of note, the region of H19 loci where rs3741219 resides expresses another antisense transcript named the H19 opposite tumor suppressor (HOTS)." (PMID 31277475, 2019). "We found that low H19 expression was significantly related with tumor size (p = 0.018), vascular invasion (p = 0.004) and distant metastasis (p = 0.035 and p = 0.012)." (PMID 31791180, 2019). "This activity as tumor suppressor is apparently in contrast with the upregulation of H19 observed under estrogen or hypoxia alone." (PMID 31426484, 2019). "Prior studies have supplied compelling evidence that some ncRNAs such as LET, Dreh, MEG3, and H19, are important players in tumor suppression." (PMID 31523930, 2019). "Reduced lncRNA H19 expression in hepatocarcinogenesis (HCG) tissues from patients with the epithelial TGF-β gene signature but increased H19 expression promoted tumor metastasis after TGF-β treatment in Hep3B cells." (PMID 31195692, 2019). "Both tumor suppressor and oncogenic functions have been reported for H19/miR-675, suggesting that its function depends on cell type." (PMID 28840253, 2018). "H19 inhibits cell proliferation in some systems but promotes proliferation in other systems and has been interpreted as both a tumor suppressor and oncogene." (PMID 29644076, 2018). "The pathological function of H19 as a non-coding RNA in tumor is recently being elucidated, although H19 has been intensively studied in epigenetic." (PMID 30451820, 2018). "Abnormal H19 expression, identified in many solid tumors, such as bladder cancer, breast cancer, liver cancer, lung cancer, plays an important role in tumor growth." (PMID 29449695, 2018). "The molecular mechanisms described so far for an oncogenic role of H19 in GBM range from H19 processing to produce miR-675 to a function as sponge for miR-29a, in turn boosting tumor angiogenesis." (PMID 29643989, 2018). "The deletion of H19 can reduce tumor cell invasion and metastasis, and increased expression of H19 can increase these two characteristics." (PMID 29891752, 2018). "High expression of H19 is associated with advanced HCC stages and prognostic significance correlates with the predictive value of tumor recurrence." (PMID 30158867, 2018). "Consistently, H19-expressing tumours showed markedly reduced proliferation as judged by Ki-67 staining." (PMID 30397197, 2018). "H19 is a multifunctional lncRNA that regulates embryo development and growth, glucose metabolism, and tumour development." (PMID 30397197, 2018).
tumor (continued). "H19 plays a role in tumor initiation and progression, the mechanisms, however, vary among cancer types." (PMID 30026672, 2018). "Other studies provided evidence that H19 functions as an endogenous miRNA sponge for let-7 tumor suppressor miRNAs." (PMID 28793797, 2018). "Clearly, these findings demonstrated that plasma levels of H19 are useful as a potential biomarker for the diagnosis of GC, particularly for early tumor screening." (PMID 29599934, 2018). "Highly expressed HOTAIR is correlated with tumor size and lymph node metastasis, while H19 can contribute to higher patient relapse." (PMID 29416703, 2018). "H19 was initially proposed as a tumor suppressor due to its capacity to suppress clonogenicity and tumorigenicity in tumor cells." (PMID 29636074, 2018). "Functionally, H19 has been shown to promote tumor growth and regulate anchorage-independent growth after hypoxia recovery." (PMID 28793797, 2018). "H19 has been reported to be upregulated and promoted various cancers; however, tumor suppressing effects of H19 has also been reported." (PMID 28840253, 2018). "Firstly, H19 is a developmental reservoir of miR-675 that suppresses the expression of many tumor suppressors." (PMID 30154386, 2018). "LncRNA H19 was one of the first imprinted lncRNAs to be discovered and is regarded as an oncofetal or tumour-suppressed gene." (PMID 30547791, 2018). "HCC patients with elevated expression of H19 in the tumor tissues showed poor DFS, suggesting a predictive role of H19 in HCC prognosis." (PMID 30105249, 2018). "Lin28 promotes malignancy by blocking the biogenesis of tumor-suppressive let-7 and by derepressing the expression of oncogenic lncRNA—H19." (PMID 30134946, 2018). "Based on those findings, a plasmid expressing diphtheria toxin under control of the H19 promoter (BC-819) has been intratumoraly injected into bladder tumour leading to a significant reduction in the tumour size in mice." (PMID 30524312, 2018). "The univariate and multivariate analysis of PFS revealed that H19 and tumor stage were independent prognostic factors." (PMID 27911863, 2017). "Understanding this complicated interplay between H19 acting as an oncogene and a tumor suppressor results in a more complex, but clearer picture of how H19 participates in each role." (PMID 28933364, 2017). "In xenograft nude mice model, studies demonstrated that H19 promotes tumor growth and tumor-initiating ability." (PMID 29299179, 2017). "AM and MS provided patient tumor tissue samples for QMSP analysis and patient tumor H19 expression data, AMPK western blot data and Ki-67 index data." (PMID 27775072, 2017). "Our results are consistent with the report that H19 and miR-675 have higher expression in adjacent tissues compared to tumor tissues." (PMID 28212565, 2017). "While H19 exhibits oncogenic functions in some types of cancer, it also acts as a tumor suppressor, depending on the type of cancer and cellular context." (PMID 27911863, 2017). "H19’s importance has been widely implicated in HCC; however, reports are inconsistent in its role of promoting cancer as an oncogene or acting as a tumor suppressor." (PMID 28933364, 2017). "H19 reduced the availability of let-7, a potent tumor suppressor microRNA that functions to suppress the expression of oncogenes important for cell growth and motility." (PMID 27902459, 2017). "There is increasing evidence that supports H19 as being a tumor suppressor acting to inhibit metastasis." (PMID 28933364, 2017). "Overexpression of H19 enhances tumor cell growth and induces EMT; additionally, H19 modulates miRNA processing through its interaction with proteins involved in this molecular process (i.e., Drosha, Dicer)." (PMID 29147648, 2017). "AMPK phosphorylation, cell proliferation, H19 levels and DNA methylation were measured in tumor tissue samples from both pre- and postoperative samples." (PMID 27775072, 2017).
tumor (continued). "While several in vivo H19 gene deletion experiments have indicated a tumour suppressor function, possibly during the early formation of tumours, increases of H19 RNA are thought to contribute to metastatic growth in the later stages of tumourigenesis." (PMID 28587163, 2017). "Our in vivo data employing H19 knockout mice showed accelerated tumor development and more aggressive tumors." (PMID 31225433, 2017). "LncRNA UCA1 functions as an oncofetal gene similar to lncRNA H19 and is detected not only in tumor tissue samples but also in blood and urine samples from bladder cancer patients as a circulating biomarker." (PMID 28969100, 2017). "Metformin induced DNA methylation at H19 promoter to down-regulate H19 expression and hence inhibit tumor cell migration and invasion." (PMID 27902459, 2017). "H19/miR-675 axis was illustrated to play essential roles in cancers through targeting oncogenic or tumor suppressive factors." (PMID 28230721, 2017). "Its role in tumor initiation and progression has long been a subject of controversy, although accumulating data suggest that H19 is a major gene involved in cancer." (PMID 29190892, 2017). "Among the targets of HIF1α is the lncRNA H19, an imprinted non coding RNA which expression was found up-regulated in many tumours including CRC, hepatocellular carcinoma, testicular cancer, choriocarcinoma, osteosarcoma, esophageal cancer and glioma." (PMID 28061476, 2017). "In concordance, knockdown of H19 markedly inhibits tumor growth and suppresses tumorigenesis in nude mice." (PMID 28102845, 2017). "All three cell lines we investigated, i.e. HepG2, Plc/Prf/5, and Huh7, showed that H19 suppresses tumor cell survival, as indicated by a reduced colony number." (PMID 31225433, 2017). "The data on reduced expression of H19 in human HCC and its chemosensitizing actions suggested tumor-suppressive actions of H19 in HCC." (PMID 31225433, 2017). "Current evidence indicates that H19 plays crucial roles in tumor metastasis, through the regulation of critical events specifically the epithelial to mesenchymal and the mesenchymal to epithelial transitions." (PMID 28427159, 2017). "Of the 4 tumors with indications for LOH of 11p15, 1 (tumor 51) showed hypermethylation of H19-DMR and hypomethylation of KvDMR." (PMID 28099933, 2017). "Although H19 has been enthusiastically studied for several years, the details of the mechanisms by which H19 functions as a tumor inhibitor or oncogene in cancer and its precise biological functions require further clarification." (PMID 27802187, 2017). "Though the role of H19 in tumor initiation and progression has long been a subject of controversy and HULC is highly over expressed in serval tumors, H19 and HULC were significantly downregulated in iCCA tissues compared with normal tissues in both studies." (PMID 28427159, 2017). "As miR-675 is derived from the first exon of H19, it also plays an important role in tumor development in an H19 dependent manner." (PMID 28212565, 2017). "The long non-coding RNA (lncRNA) H19 represents a maternally expressed and epigenetically regulated imprinted gene product and is discussed to have either tumor-promoting or tumor-suppressive actions." (PMID 31225433, 2017). "The authors also showed that CTCF is frequently hemizygous in human tumours, and interestingly, among the human tumours investigated, the H19 locus was frequently found to be hypermethylated, as was the case in the hemizygous mice." (PMID 28587163, 2017). "An H19 knockout mouse model (H19Δ3) showed increased tumor development and tumor cell proliferation after treatment with the carcinogen diethylnitrosamine (DEN) independent of the reciprocally imprinted insulin-like growth factor 2 (IGF2)." (PMID 31225433, 2017). "It has been reported that lncRNA H19 can play either oncogenic or tumor suppressive role in the progression of diverse cancers." (PMID 28103585, 2017).
tumor (continued). "In a previous study, H19 was shown as one of the most increased lncRNAs with a ~8.91-fold change in human primary GC tumors comparing with non-tumor tissues." (PMID 28230721, 2017). "As already described for other lncRNAs, H19 can work as a microRNA sponge or epigenetic modulator moreover, it is a reservoir for microRNA-675 (miR-675-5p and miR-675-3p) by which H19 seems to promote tumour growth and metastasis." (PMID 28061476, 2017). "Epigenetic changes are involved in cancer metastasis in HCC and H19 has been shown to impact pathways, resulting in epigenetic changes and leading to tumor suppression." (PMID 28933364, 2017). "With its effect on HCC cancer cell growth, chemosensitivity, and carcinogenesis, H19 shows tumor-suppressive actions." (PMID 31225433, 2017). "In vivo, tumor volumes were decreased significantly in H19 silenced group compared to the control group, but was attenuated by co-transfection of shRNA-H19 and miR-342-3p inhibitor, which were stablely constructed through lenti-virus vector." (PMID 27716361, 2016). "Recent studies reported that H19 promoted tumor metastasis via miR-675 and accelerated the epithelial-to-mesenchymal transition (EMT) progression." (PMID 27429196, 2016). "The migration, proliferation and invasion of the tumor cells were able to be significantly inhibited by the knockdown of H19 in vitro." (PMID 27825121, 2016). "At the end of the fourth weeks, the mice were sacrificed and tumors excised, we found that H19 knockdown significantly reduced the tumor volume of NOZ cells when compared with control group." (PMID 27716361, 2016). "Research into the role of H19/miR-675 in tumor metastasis has similarly lead to contradictory findings." (PMID 26623562, 2016). "The H19 was recently reported as a molecular sponge to antagonize let-7, which was well-known as a tumor-suppressive microRNA." (PMID 27825121, 2016). "An association between lncRNAs and the immune response has only recently emerged, and only a few have been shown to be expressed in endothelial cells, and adipocytes, with preferential expression of MEG3 and H19 observed in tumour stroma." (PMID 27685983, 2016). "Human MYOD1 gene is located at 11p15, a chromosomal region containing the IGF2 and H19 imprinted genes, whose expression has been found to be altered (over-expression of IGF2 and downregulation of H19) in a subset of ERMS tumours." (PMID 27764816, 2016). "H19 promotes tumor cell migration and invasion by sponging let-7, thus relieving the inhibitory effect of let-7 on its targets, resulting in an increase of metastasis-promoting genes including Hmga2, c-Myc and Igf2bp3." (PMID 26623562, 2016). "After H19 gene is knocked out, the capacity for tumor growth, invasion and metastasis is enhanced in murine models of colon tumorigenesis." (PMID 26637808, 2016). "Through this action, H19 plays a role in regulation of muscle cell differentiation, glucose metabolism, tumor metastasis, and endometrial development." (PMID 27223264, 2016). "Recently, numerous studies indicate that H19 plays a key role in tumorigenesis, but the results have been disputed, especially in the aspects of tumor progression and metastasis." (PMID 27672656, 2016). "In summary, the expression of H19 can be detected in liver metastasis whatever the primary tumor, with variable levels of expression from patient to patient." (PMID 26623562, 2016). "BrdU staining of the tumor tissue revealed reduced cell proliferation in H19 shRNA treated mice (p < 0.01), further confirming the stimulatory role of H19 during LSCC development." (PMID 26872375, 2016). "We have previously reported that H19 promotes migration and invasion of tumor cells by decreasing the bioavailability of microRNA let-7." (PMID 27223264, 2016).